AR (androgen receptor)
Diseases named in the same sentence as AR in open-access papers (continued):
Sharing a sentence is not in itself a finding about the gene and the disease.
tumor (continued). "In ER-negative breast cancers, the existence of AR-dependent, and ER-independent tumor cell growth is related to the adverse prognostic effect of AR positivity, especially in the triple-negative subtype." (PMID 32290220, 2020). "The authors showed that patients with mCRPCa exhibiting nuclear localized AR-V7 in circulating tumor cells had better outcomes when treated by taxanes than by AR signaling inhibitors." (PMID 33255593, 2020). "CTBP1-AS modulates the global epigenetic status to repress negative cell cycle regulators or AR corepressor, CTBP1, to promote tumor growth and activation of AR activity." (PMID 32704143, 2020). "In PCa, androgen receptor (AR) can bind intronic binding sites near the tumor translocation sites and further promote spatial proximity in a ligand-dependent way." (PMID 33168103, 2020). "GSA0932 has stronger cytotoxic activity against AR-positive tumor cells than non-AR expressing cells." (PMID 32477465, 2020). "Androgen and Androgen Receptor (AR) signaling are critical not only for the development and function of normal prostate but also for tumor development and are thus widely used as therapeutic targets." (PMID 32256978, 2020). "Any alterations to AR-mediated transcription can have a profound effect on carcinogenesis and tumor growth." (PMID 32047165, 2020). "Oral administration of carnosol (30 mg/kg/day) 5 days per week for 4 weeks to athymic nude mice implanted with AR and ER-α positive 22Rv1 cells reduced tumour growth by 36% and reduced serum prostate specific antigen levels by 26%." (PMID 33049974, 2020). "By univariate analysis, age (HR 1.99, 95% CI 1.09–3.61, p = 0.02), tumor stage (HR 5.3, 95% CI 2.7–9.9, p < 0.001), and levels of (high vs. low) AR expression (HR 6.6, 95% CI 1.4–31.17, p = 0.016) were significant predictors for distant metastasis." (PMID 32778063, 2020). "In primary tumours, weak but positive correlations were observed between the AR and cytoplasmic (rs = 0.33; P < 0.0001; r2 = 12.4%) and nuclear (rs = 0.20; P = 0.005; r2 = 3.76%) UGT2B17 staining." (PMID 32047296, 2020). "On the other hand, p300 can also serve as an enhancer of c‐Myc, c‐Myb, and AR to promote tumour growth." (PMID 32951317, 2020). "Yet, androgen receptor (AR) usually remains as a major regulator of tumor cell proliferation in CRPC." (PMID 32562083, 2020). "Binding of NCL to this G4-element is required for NCL to suppress AR expression, specifically in AR-expressing tumor cells." (PMID 32477465, 2020). "The first mechanism illustrated that PC cells became more sensitive with decrease in the androgen threshold although androgen was sufficiently overexpressed to activate the AR because of in situ intra-tumour and adrenal gland synthesis." (PMID 33303035, 2020). "This lineage transition enables tumor cells to evade androgen receptor (AR) pathway inhibitors such as enzalutamide by shedding their dependence on the AR pathway." (PMID 33328604, 2020). "Induction of AR initiates Tam-resistance (TamR) in HR+ BCa cell models and promotes tumor growth in mouse xenografts, highlighting a role for AR in ET-R and disease progression." (PMID 32948192, 2020). "To extend our findings in mice to human HCC, we analyzed TLR4 and AR expression using tissue microarray, containing matched pairs of tumor and peritumoral liver tissue from 22 male and 8 female patients with primary HCC." (PMID 31956356, 2020). "Postmenopausal women with ER-positive, AR-positive (ER+/AR+) tumours showed significantly better OS than postmenopausal women with ER-positive, AR-negative (ER+/AR-) tumours (p = 0.030)." (PMID 32928183, 2020). "AR can modulate the expression of TFs, biomarkers and vital tumour promoters in PrCa development, such as KLK2, KLK3, MYC, MSMB and TMPRSS2." (PMID 32397189, 2020). "For example, several reports have indicated that GR activity was enhanced after therapeutic inhibition of AR signaling, which contributed to tumor-promoting PCa cell viability." (PMID 33542904, 2020).
tumor (continued). "Effects of specific STAT5a/b knockdown on cell viability and AR signalling also seem to be dependent on the cellular background of the resistant cells, reflecting the challenges of tumour heterogeneity in therapy treatment of late-stage diseases again." (PMID 32790723, 2020). "Where tissue blocks were available, tumor type, grade, estrogen receptor (ER), progesteron receptor (PgR) and androgen-receptor (AR) status as well as HER 2 and Ki67 were performed." (PMID 32108307, 2020). "Taken together, we propose a model that describes the bimodal action of miR-299-3p as a tumor suppressor in PCa by targeting both AR and VEGFA simultaneously." (PMID 32198489, 2020). "Conversely, the androgen receptor mediates the angiogenetic and immune response to neoplasia in several tumour models." (PMID 32183012, 2020). "Androgen receptor (AR), the first effector of testosterone action, activates certain genes involved in tumor growth and metastasis." (PMID 33224867, 2020). "On univariate Cox regression analysis ER+/AR+ tumours showed significantly better OS than ER+/AR- tumours (p = 0.047) and ER-negative, AR-negative (ER−/AR-) tumours showed significantly better DFS than ER-negative, AR-positive (ER−/AR+) tumours (p = 0.036)." (PMID 32928183, 2020). "USP22 plays an important role in AR protein stability and recruitment to AR-binding regions to drive AR driven cancer cell proliferation and tumor growth in CRPC cells." (PMID 34660907, 2020). "Silencing KLF5, in turn, reduced AR transcriptional activity and inhibited androgen-induced cell proliferation and tumor growth in vitro and in vivo." (PMID 32245249, 2020). "The combination of SNPs with thehistopathological tumor data between allele variants of AMACR,AKT1+AR, and AKT1+AMACR indicated an associationwith protection against seminal vesicle invasion." (PMID 32484847, 2020). "ER+/AR- tumours had a significantly worse OS than ER+/AR+ tumours (p = 0.015) and ER−/AR+ tumours had significantly worse DFS than ER−/AR- tumours (p = 0.014)." (PMID 32928183, 2020). "Transcriptome sequencing revealed that PBK is a mediator of global AR signalling with key roles in regulating tumour invasion and metastasis." (PMID 30237440, 2019). "Our result that AR low tumor significantly enriched DNA repair gene sets aligns with this notion that tumors with AR low expression have more DNA damage because of the lack of the protection by AR and it enriched DNA repair gene sets as a response." (PMID 31151151, 2019). "We then tested an available pharmacological sGC inhibitor on treating TMPRSS2-ERG-positive xenograft tumors and showed that inhibitor treatment alone or in combination with enzalutamide (an AR antagonist) can significantly suppress PCa tumor growth." (PMID 30718921, 2019). "Overall, this study demonstrates that targeting antiapoptotic BCL2 protein signaling in combination with AR inhibition results in enhanced tumor cell killing, suggesting this is a promising therapeutic strategy with the potential for clinical development." (PMID 31228231, 2019). "Given that VCaP and CWR22Rv1 cells express multiple AR-Vs, a phenomenon observed in circulating tumour cells, it is important that new models express several clinically-relevant AR-Vs to mimic CRPC." (PMID 31006810, 2019). "AR expression in LAR subtype tumors is responsible for tumor cell viability and survival, with knockdown of AR expression significantly reducing the ability of LAR cell lines to form colonies." (PMID 31527644, 2019). "To date, most reports on hormone receptor genomics, including ERα and AR, made use of cell line models, and only slowly, reports on genome-wide chromatin binding in the context of human tumor tissue are being released." (PMID 30620009, 2019).
tumor (continued). "A better understanding of the relationship of AR, clinical characteristics, and patient outcomes is needed to further individualize patient care based on tumor biology." (PMID 31840050, 2019). "As for the ER+ BRCA vs. PRAD case, the correlation networks for the genes selected were obtained for the AR+ TNBC vs. PRAD tumor and normal samples." (PMID 31238876, 2019). "We considered 159 BC patients with available primary tumor samples and data on AR and ER expression, of whom 125 patients had luminal tumor (defined as ER ≥1% and/or PgR ≥1% with any Ki67 or HER2 values)." (PMID 31110518, 2019). "The interaction of AR with co-activators critically regulates receptor functions and compounds that interfere with this binding impact on tumor growth." (PMID 31192191, 2019). "TNBC tumours expressing AR have also been shown to be highly enriched for PIK3CA kinase mutations both in cell lines and patient samples." (PMID 31769425, 2019). "For all three tumor types, a substantial increase in data quality was observed for ERα, AR, and FOXA1 with strong increased peak intensity, as compared to single fixation procedure using FA." (PMID 30620009, 2019). "By analyzing AR-FL from CTC samples we seem to largely avoid such transcripts from non-tumor sources as AR expression in normal blood cells is known to be minimal or null." (PMID 31288377, 2019). "Using the functional definition of the AMS, the AR cistrome was found to be normal‐like in all 18 normal tissues and tumor‐like in all 16 tumor tissues." (PMID 31520575, 2019). "IHC examination of AR expression in the PC tissue of subgroups E2 and E3 showed a clear nuclear reaction in tumor cells and in single cells of the peripheral tumor stroma." (PMID 31582998, 2019). "Another study demonstrated that omega-3 PUFA treatment slowed castration-resistant tumor growth and accelerated androgen receptor protein degradation." (PMID 31052319, 2019). "Additional strengths of this analysis include the use of central pathology assessment of AR and other tumor markers, as well as the evaluation of a continuous measure of AR expression." (PMID 30795773, 2019). "Patients with AR+ tumor showed worse DDFS as compared to AR- patients: 5 years DDFS rates were 67.2 and 80.6%, respectively (log-rank p = 0.018)." (PMID 31245286, 2019). "These experiments provide robust experimental evidence for the key role of PBK in sustaining AR levels and tumour growth, indicating that PBK is an essential player in PrCa cell survival and invasion." (PMID 30237440, 2019). "We report the radiosensitizing effect of anti-androgens, which showed synergism in combination with EBRT in AR-expressing tumor slices and cell lines." (PMID 31635359, 2019). "A possible justification to this is the fact that ADT aims to target all the transcription/translation-related activities of AR, which are typical of tumor epithelial cells." (PMID 31616657, 2019). "In mouse xenograft models, DHT treatment resulted in significant induction of tumor growth, and an AR inhibitor enzalutamide antagonized the DHT effects." (PMID 30791431, 2019). "As siRNA is not yet a reliable method for treatment in vivo, therefore we next tested the effect of combined antagonism of full-length AR plus inhibition of ATM on CRPC tumor growth in vivo." (PMID 31083651, 2019). "From WGS and ChIP-seq data, we show the potential relevance of recurrent alterations in non-coding regions identified with WGS and highlight the central role of AR signaling in tumor progression." (PMID 31748536, 2019). "Another AR variant coactivator is DBC1 protein, which directly interacts with AR-V7, and its inhibition results in AR-V7 degradation and reduced tumor growth." (PMID 31877956, 2019). "Preclinical evidence shows that the AR effect depends on tumor subtype: in estrogen receptor-positive cancer cells AR activity is able to inhibit tumor growth, whereas in TNBC AR seems to retain an oncogenic effect." (PMID 31245286, 2019).
tumor (continued). "Primary tumors of MetB patients also showed low AR staining in the tumor stroma coupled to a reactive stroma response." (PMID 31162796, 2019). "To confirm and validate these and other findings on the proteome level we performed immunohistochemical analyses for EGFR, MET, CA12 and AR on a number of tumours with low or high FPM values for the corresponding genes." (PMID 31747973, 2019). "LAPC4 xenograft tumours (which exhibit a wild-type androgen receptor and features of hormone-dependent growth and metastasis) treated with pomegranate demonstrate delayed regrowth following castration with a reduction in the increased levels of NF-κB activity." (PMID 31540470, 2019). "The striking finding that knocking down endogenous LRIG1 in 3 AR+ PCa models promotes tumor regeneration/growth suggests that LRIG1 intrinsically represses tumorigenicity of AR+ PCa cells." (PMID 31792211, 2019). "Recent studies report that the dysregulation of AR signalling by inhibition of AR via ATTs influences tumour cell plasticity by activation of EMT-inducing markers and pathways." (PMID 30194451, 2019). "In advanced cancer, hormone deprivation therapy effectively blocks tumour growth, but typically within 2 years, hormone-independent cells emerge, which frequently still require the AR for growth and will lead to the death of the patient." (PMID 31589603, 2019). "Specifically, tumour heterogeneity together with changes in ER and AR transcriptional activity, are responsible for endocrine therapy resistance." (PMID 30832393, 2019). "Androgen deprivation therapy (ADT), also known as chemical castration, is primarily used to decrease tumor size through downregulation of AR signaling." (PMID 31771198, 2019). "RSV inhibits the androgen receptor signalling in tumour prostatic cells, inhibiting cell proliferation." (PMID 30832393, 2019). "Mechanistically, neighboring adipocytes significantly increase the expression of miRNA-301a in tumor cells, which serves to suppress AR signaling in these cells." (PMID 30925918, 2019). "The expression of M2 macrophage‐specific protein markers increased with the upregulation of AR after adjusting for tumor purity." (PMID 31355524, 2019). "Collectively, our study indicates that LRIG1 represents a pleiotropic AR-regulated feedback tumor suppressor that functions to restrict oncogenic signaling from AR, Myc, ERBBs, and, likely, other oncogenic drivers." (PMID 31792211, 2019). "In summary, we have demonstrated that CRPC 22Rv1 tumor growth is resistant to AR antagonist or ATMi as monotherapies, but is significantly inhibited by combined treatment." (PMID 31083651, 2019). "IHC revealed positive nuclear staining for mouse AR in spindle-like tumor cells, suggesting an origin of the AR-positive luminal epithelial cells (Fig 4C2)." (PMID 30677079, 2019). "Archived primary tumour tissue or a direct biopsy of the metastatic lesion is required to assess the AR expression status in cases where an AR-targeted therapy is considered." (PMID 31718606, 2019). "In some studies involving TNBC cases, the presence of AR appeared correlated to an increase in overall mortality, lymph node metastasis and higher tumor stage." (PMID 30941159, 2019). "To further validate KDM8 as a critical coactivator of AR in prostate carcinogenesis, we wish to identify the recruitment of KDM8 to the promoters of AR target genes involved in tumor progression." (PMID 30072740, 2019). "The tumor cells also showed positive staining for endogenous mouse AR, E-cadherin, and CK8 (Fig 3D3-5), the hallmarks of prostatic luminal epithelium." (PMID 30677079, 2019). "Based on findings derived mostly from cell culture studies and a few in vivo animal cancer models, the functions of VDR, PPARs, AR, ER and GR in tumor-supporting cells are relatively well-characterized." (PMID 30925918, 2019). "Subsequently, we investigated the effects of apalutamide on IR sensitivity in androgen-dependent, AR-positive PC295 ex vivo tumor slices." (PMID 31635359, 2019).